CD70 (CD70 molecule)
Diseases named in the same sentence as CD70 in open-access papers (continued):
Sharing a sentence is not in itself a finding about the gene and the disease.
tumor (continued). "CD70 in epithelial cells and fibroblasts may thus coordinate tumor progression by directly activating MAPK and NF-κB in tumor cells while indirectly sustaining immune evasion." (PMID 41510255, 2025). "Consequently, there is considerable interest in developing chimeric antigen receptor (CAR) T-cell therapy products that can specifically target CD70 in various neoplasms, including AML." (PMID 38388965, 2024). "Indeed, myeloid cells associated with a favourable clinical response expressed transcripts associated with tumour-residing CCR7+ DCs, including CCR7, CD274, IL15, PVR and CD70." (PMID 38267413, 2024). "Collectively, these results suggest that CD70 might play a fundamental role in DLBCL clinical outcomes by regulating the tumor-immune microenvironment." (PMID 39446784, 2024). "This improved activation was also converted to improved killing of CD70+ tumor cell lines compared to CD70-CAR NK cells (Viable Raji: 16.8 ± 5.5% vs 25.9 ± 4.5%, viable PANC-1: 31.1 ± 5.9% vs 59.6 ± 4.2%, viable LIM2099: 45.3 ± 11.5% vs 85.5 ± 3.9%, respectively)." (PMID 38331849, 2024). "Also, in the same study, the addition of the poly (ADP-ribose) polymerase (PARP) inhibitor olaparib (OLA) associated with CD70 CAR-T showed an increase in CD8 + infiltration and a better survival rate among tumor-bearing mice." (PMID 38195534, 2024). "The CD70 expression has been suggested to help tumor immune evasion and accelerate tumor growth." (PMID 39261955, 2024). "Notably, Allogene Therapeutics has reported the success of CD70 scFv-based allogeneic CAR-T cells (ALLO-316) exhibited potent anti-tumor activity." (PMID 38637886, 2024). "Our findings suggest that CD70 may contribute to the pathophysiological processes of DLBCL by modulating the tumor-immune microenvironment." (PMID 39446784, 2024). "Both co-expression network and immune cell infiltration analyses suggested that CD70 may contribute to DLBCL pathophysiology by modulating the tumor-immune microenvironment." (PMID 39446784, 2024). "We hypothesized that CD70-expressing tumor cells and CAFs could be effectively eliminated by CAR NK cells." (PMID 38331849, 2024). "Furthermore, adding an IL-15 cytokine cassette to the mRNA CAR construct drastically improved CD70+ tumor and CAF cell killing in both basic and advanced models." (PMID 38331849, 2024). "As a consequence, patients with advanced ICI‐resistant tumours may specifically benefit from treatment combined with anti‐CD70 mAbs." (PMID 38468489, 2024). "Furthermore, we assessed if CD70+ tumor cells and CAFs can be eliminated by CD70-directed CAR NK cells using in vitro and in vivo models that are representative for the clinical situation of CD70+ tumors." (PMID 38331849, 2024). "Additionally, we show that armoring CD70-CAR NK cells with IL-15 is a prerequisite for effective eradication of low- and high-expressing CD70+ tumor cells and CAFs." (PMID 38331849, 2024). "However, the function of CD70 concerning apoptosis in cancer is complex and varies depending on the tumor microenvironment." (PMID 39598439, 2024). "In addition, CD70-targeting CAR NK cells were developed to assess cytotoxic activity against CD70+ tumor cells and CAFs, and the effect of cytokine stimulation on their efficacy was evaluated." (PMID 38331849, 2024). "All CD70 VHH CAR-T cells eliminated tumor cells for at least 7 consecutive cocultures." (PMID 38637886, 2024). "Interestingly, CD70-CAR NK cells demonstrated to be highly competent in eliminating both CD70+ tumor cells and CAFs when stimulated with interleukin (IL)-15." (PMID 38331849, 2024). "In tumour cell lines and animal xenograft models, it was discovered that CD27z‐CARs, which comprise CD70 ligand and CD3z chain fusion, displayed superior proliferative and anticancer activity than CD70 scFv CARs while retaining normal HSCs." (PMID 38712978, 2024). "We developed a CD70-CAR NK cell therapy to specifically eradicate CD70+ tumor cells and CD70+ CAFs." (PMID 38331849, 2024).
tumor (continued). "In this study, we identified CD70 as a target for tumor cells and CAFs in CRC and PDAC patients." (PMID 38331849, 2024). "Consequently, CD70 is an increasingly recognized target for developing antibody-based therapies, but its expression patterns vary among different tumor types in spatial distribution, magnitude of expression and percentage of positive cells." (PMID 37093350, 2023). "Additionally, IMM40H can inhibit growth signals and/or limit the acquisition of T-cell immune regulatory function inside the tumor microenvironment, while removing CD70+ malignant cells through Fc-mediated effector activities." (PMID 37849799, 2023). "Studies on CD70 expression in tumor states have found that there is an overexpression of CD70." (PMID 37174089, 2023). "In addition to immune checkpoints (PD-L1/L2, LAG3, TIM-3) strongly expressed IL1R2 and CD70 can inhibit immune responses and create a tolerogenic tumor microenvironment (TME)." (PMID 37495858, 2023). "Moreover, chronic CD27/CD70 engagement maintains DCs in a tolerogenic state and favors the expansion of peripheral Tregs, suppressing anti-tumor immune responses." (PMID 37371818, 2023). "In this study, we developed an immunoPET tracer for molecular imaging of tumor CD70 expression." (PMID 37093350, 2023). "However, a high expression of CD70 is believed to be related to mechanisms of immunotolerance of tumor cells against the host immune system." (PMID 37763107, 2023). "As assessed by acoustic force microfluidic microscopy evaluating the cellular binding avidity between the CD70 specific CAR T cells and AML tumor cells, CD70 specific CARs with the CD8α hinge conferred augmented binding avidity on T cells as compared to CD27 hinge CARs." (PMID 38090558, 2023). "One team constructing CD70 CAR-T for AML found that when AML exposure to AZA at physiologically dose-dependent concentrations increased the expression of CD70 antigen in tumor cells and enhanced the efficacy of CD70 CAR-T, then they demonstrated this in mice models." (PMID 36701037, 2023). "Similarly, tumor inhibition has been observed after CD70-CAR-T cells infusion; however, mice bearing leukemic cells eventually relapsed." (PMID 36845088, 2023). "However, the activity of anti-CD70 antibody–drug conjugates relies on the internalization of the drug, which can significantly differ among tumor cells." (PMID 37371818, 2023). "Even when expression of CD70 is limited on tumor cells, it can find its way to sustain a tumor enhancing environment by hijacking other important players within the TME that contribute to the proliferative and invasive behavior of cancer, such as the cancer-associated fibroblasts (CAFs)." (PMID 34991665, 2022). "Anti-CD70 therapy has emerged as a new tumour immunotherapy approach." (PMID 35222533, 2022). "Although CD70 is prevalent in numerous cancers, CD70 expression patterns may vary among these different tumor types in spatial distribution, intensity of expression and percentage of positive cells." (PMID 34991665, 2022). "Furthermore, compared with IgG treatment, inhibition of CD70 and PD‐L1 resulted in significant growth retardation of tumours." (PMID 36471481, 2022). "Moreover, when comparing canine OSCC tumor gene expression to normal oral mucosa, two differently expressed genes associated with the presence of TAMs and MDSCs were identified: CXCL2, CD70." (PMID 36698398, 2022). "Previous studies have shown that the expression of CD70 in B-cell malignant tumors may play a role in immune escape and enhance tumor survival and growth." (PMID 36239354, 2022). "CD70 is differentially expressed in distinct tumor subtypes and in individual tumors as well." (PMID 36338731, 2022). "When immune evasion results from CD70 genetic alterations, restoring adequate T‐cell priming may augment tumour immunity." (PMID 36471481, 2022). "Finally, genetic inhibition of CD70 in the mouse model will help to further evaluate the tumour microenvironment in vivo." (PMID 36471481, 2022).
tumor (continued). "Heterogenous intra-tumor CD70 protein expression on carcinoma (or RMC tumor) cells was found in 80% (4/5; including Patient 1) of the primary tumors tested (as quantified by H-score), substantiating the discovery that CD70 is expressed in a sub-population of transformed RMC cells." (PMID 35837094, 2022). "Here, we have investigated whether the CD70/CD27 axis is also involved in Treg-mediated suppression of anti-tumor immunity." (PMID 34423375, 2022). "Notably, except in haematopoietic and lymphoid malignancies, CD70 genetic alterations were extremely rare in cancers, as mutations and/or CNV loss were observed in less than 1.5% of 35 993 tumour samples included in the COSMIC database." (PMID 36471481, 2022). "In summary, we report the successful synthesis and characterization of peptide amphiphile micelles incorporating siRNA targeted to HIF2α and CD70-targeting peptides and their ability to exert multiple anti-tumor effects in patient-derived ccRCC cells and tumor tissues." (PMID 36500549, 2022). "Here, authors showed that CD70 targeting antibodies could inhibit proliferation of chemo-resistant tumor cells." (PMID 34991665, 2022). "CD70, mainly expressed on T cells, B cells, and tumor cells, leads to activation of immune cells." (PMID 35216458, 2022). "Therefore, blocking the expression of CD70 in tumor cells has become another strategy of antitumor-targeted therapy." (PMID 36239354, 2022). "Interaction of the MHC/tumour antigen epitope complex with the T‐cell receptor and costimulatory signals (including CD70/CD27) may lead to the activation of CD4+ and CD8+ T cells." (PMID 36471481, 2022). "Previous studies have reported that CD70 is overexpressed in various tumours." (PMID 35222533, 2022). "Notably, higher CD70 expression on tumour cells was observed in the patients diagnosed with a more advanced stage of disease." (PMID 36471481, 2022). "CD70 is a critical mediator of immunocytes’ activation in the tumor microenvironment." (PMID 34603309, 2021). "CD70 can promote the proliferation and differentiation of tumor cells in metastatic tissues, indicating that CD70 may be considered a novel predictive factor for metastasis." (PMID 34367975, 2021). "Thus, our result would argue for a tumor suppressor role for CD70, although further analyses would be required to dissect the function of the CD27–CD70 axis in tumorigenesis." (PMID 33996677, 2021). "Furthermore, we identified potential molecular targets based on our expression data in NE-low and immune-oasis tumor subsets, including CD70, ANXA1, ITGB6, TP63, IFI27, YBX3 and CXCR2." (PMID 34200100, 2021). "This trend suggests that CD70 expressed in tumor tissue represses anti-tumor immunity via CD27." (PMID 35145909, 2021). "A recent study showed that LMP1 signaling in B cells led to an overexpression of tumour associated antigens presented on MHC-I and II, and the upregulation of costimulatory ligands CD70 and OX40L, thereby inducing potent cytotoxic CD4+ and CD8+ T-cell responses." (PMID 34956172, 2021). "Moreover, it was demonstrated that CD70 plays a crucial role in evoking immune surveillance by recruiting CD27+ regulatory T-cells (Treg) to the tumor site." (PMID 34200100, 2021). "ARGX-110 is an IgG1 mAb that targets CD70 on tumor and Treg cells to prevent immune exhaustion." (PMID 33980266, 2021). "Overexpression of CD70 by tumor cells leads to chronic activation of T cells and immune exhaustion." (PMID 33980266, 2021). "In addition, the correlation of the CD70-positivity of tumor cells and CD27-positive TIL on survival was analyzed." (PMID 35145909, 2021). "Also, cells in TME interact with each other and with the neoplastic cells through different suppressor receptors like PD-1, CTLA-4, CD70 and gangliosides that increase the tumour immune escaping." (PMID 33804731, 2021).
tumor (continued). "In our study, TanCAR-T cells distinctively recognized either B7-H3 or CD70 and enhanced their effector function as judged by tumor-lytic activity when both targets were encountered simultaneously while stimulation of unispecific CAR-T cells only resulted in suboptimal activity." (PMID 32685008, 2020). "Among genes encoding costimulatory molecules, CD70 and CD80 were similarly expressed by FL and normal GC B cells, while CD86 was significantly overexpressed in tumor cells (p = 0.004), and could contribute to the activation of Tfh after binding to CD28." (PMID 33028033, 2020). "To further assess the specific antitumor efficacy of TanCAR-T cells, we performed another in vivo experiment wherein established xenografts of tumor expressing CD70-/B7-H3+, CD70+/B7-H3- and CD70-/B7-H3- (Fadu, A375B7-H3 Ko and K562 cell lines) were treated with TanCAR and NT T cells." (PMID 32685008, 2020). "Therefore, the constitutive CD70 expression on tumor cells lets them evade the elimination by the host immune system." (PMID 33287223, 2020). "To conclude, CD70 was strongly expressed in ccRCC tumor tissue and could serve as a ccRCC-specific exosome marker." (PMID 33276608, 2020). "The results indicated that most of tumor tissues were B7-H3 or CD70 positive." (PMID 32685008, 2020). "CD70 expression was increased in tumor samples compared to normal tissue." (PMID 33276608, 2020). "Interestingly, CD27 on malignant B cells triggers CD70 reverse signaling in NK cells, resulting in increased numbers of tumor-infiltrating activated NK cells and prolonged survival of CD27-expressing lymphoma-bearing mice." (PMID 31186046, 2019). "The CD70 CAR platform was employed for improving the clinically relevant tumor models." (PMID 31488817, 2019). "In addition, our results hold potential relevance for the treatment of other CD70+ malignancies and for understanding the role of CD70 in tumor progression." (PMID 31488817, 2019). "Twenty-eight MCL tumour samples (43%) had a very low CD70 expression (< 10%)." (PMID 31652572, 2019). "Consequently, differences in the use of antibody clones and in thresholds for positivity lead to discrepancies in the percentage of CD70 positive cases within identical tumour types, pointing out the need for one uniform and validated methodology." (PMID 31652572, 2019). "We observed different CD70 staining intensities amongst the tumour types." (PMID 31652572, 2019). "In addition, CD70 seems to be involved in the recruitment of CD27-positive Tregs to the TME thus allowing tumor evasion." (PMID 29387053, 2017). "The ADC, SGN-75, conjugated with the microtubule inhibitor auristatin, has also demonstrated potent activity in preclinical tumor models and was the subject of a clinical trial in CD70-positive NHL and metastatic RCC patients (see clinical trial number NCT01015911)." (PMID 28915592, 2017). "The specificity and mode of action (MoA) are therefore anticipated to depend on both the targeting effect of the antibody to CD70 to the tumor cells and the emission of high energy alpha-particles inducing DNA double strand breaks (DSBs) resulting in G2 cell cycle arrest and cell death." (PMID 28915592, 2017). "We observed, that P2Et-treated mice had higher numbers of spleen conventional DCs (CD45+, CD220−, CD11c+) with increased surface expression of co-stimulatory molecules such as CD86, CD40, MHCII and CD70, suggesting that in vivo P2Et treatment actually enhances the immunogenicity of tumor cells." (PMID 27253407, 2016). "Moreover, 75% of cases with CD70+ tumor cells showed poor response to first-line treatment with a progression-free survival interval of less than 1 year (data not shown)." (PMID 25951351, 2015). "Finally, in this study, a positive correlation between IHC and flow cytometric analysis of CD70 expression was established, indicating that IHC is a suitable method for assessment of tumor samples for ADCC activity of ARGX-110." (PMID 25951351, 2015).
tumor (continued). "Notably, of the one patient (p404) with tissue and primary cultures from consecutive tumors, a majority of cells of the local recurrent tumor (L3312) showed strong CD70 expression, whereas only a few cells were weakly positive in the primary tumor (L2826)." (PMID 25792975, 2015). "Furthermore, in this report the expression of CD27, the receptor for CD70, was examined in tumor cells and their microenvironment." (PMID 25951351, 2015). "Through its ligand, CD27, the upregulation of CD70 by tumor cells can facilitate evasion of the immune system by three important mechanisms: induction of T cell apoptosis, skewing T cells towards T cell exhaustion, and increasing the amount of suppressive Tregs." (PMID 26605342, 2015). "Although expression of CD70, a member of the tumor necrosis factor family, is normally restricted to activated T and B cells and mature dendritic cells, constitutive expression of CD70 in tumor cells has been described." (PMID 26605342, 2015). "As a result, suppression of the anti-tumor response might easily be established through binding of CD70+ cells to CD27+ Tregs, leading to a new immune escape mechanism in NSCLC." (PMID 25951351, 2015). "Moreover, CD27-expressing tumor infiltrating lymphocytes were found adjacent to the tumor cells, suggesting active CD70-mediated signaling." (PMID 25951351, 2015). "Acute challenge with CD70+ tumor cells was shown to induce anti-tumor T cell-mediated immunity." (PMID 25792975, 2015). "Therefore, we analyzed and compared CD70 expression in available frozen specimens of our collection of parental tumor specimens (n = 4) and corresponding primary cultures." (PMID 25792975, 2015). "In addition, if conjugated to cytotoxic drugs anti-CD70 antibodies can mediate direct anti-tumor effects." (PMID 25792975, 2015). "Furthermore, tumor infiltrating lymphocytes surrounding CD70+ tumor cells, showed a trend towards increasing FOXP3 expression and higher CD4/CD8 ratios." (PMID 25951351, 2015). "In some tumor-transformed B cells, CD70 (downstream) signaling may affect proliferation and apoptosis." (PMID 25792975, 2015). "CD70 expression also leads to generation of memory T-cell response to secondary tumor challenge." (PMID 24855562, 2014). "In addition, several long-term survivors from the group injected with CD70-modified cells demonstrated resistance to tumor re-challenge." (PMID 24779345, 2014). "The activatory effect of CD70/CD27 pathway can be exploited for anti-tumor therapy." (PMID 23450201, 2013). "Development of murine mAbs for robust and extensive screening of FFPE samples coupled with the detection of anti-tumour activity in novel indications provide rationale for expanding the application of SGN-75 for the treatment of multiple CD70 expressing cancers." (PMID 20664585, 2010). "We are currently looking at CD70 tumour expression on patients entering our Phase I clinical trial." (PMID 20664585, 2010). "The intensity and pattern of CD70 expression in these tumours are highly variable." (PMID 20664585, 2010). "Anti-tumour activity of SGN-75 correlates with higher levels of CD70 expression, suggesting that expression may be one factor that contributes to its activity in solid tumour indications." (PMID 20664585, 2010). "Next, we tested the anti-tumour activity of SGN-75 in vivo using CD70+ tumour xenografts." (PMID 20664585, 2010). "More recently, we also reported on expression of CD70 in other haematologic tumour types." (PMID 20664585, 2010). "Using these reagents we were able to extensively analyse CD70 expression in multiple tumour types." (PMID 20664585, 2010). "However, clinical testing of SGN-75 in these malignancies must be coupled with an effective method to prospectively evaluate the effect of variable CD70 expression on anti-tumour activity." (PMID 20664585, 2010).